LMTK3 (lemur tyrosine kinase 3)
Diseases named in the same sentence as LMTK3 in open-access papers (continued):
Sharing a sentence is not in itself a finding about the gene and the disease.
gastric cancer (3 papers, 2017 to 2021). A primary or metastatic malignant neoplasm involving the stomach. "It has also been reported that LMTK3 was an oncogene and a significant prognostic marker in colorectal cancer, lung cancer, gastric cancer, gastrointestinal stromal tumor and melanoma." (PMID 32865871, 2020). "In addition, a Kaplan–Meier analysis showed that high levels of LMTK3 are a negative prognostic marker in gastric cancer." (PMID 34582708, 2021).
lung carcinoma (3 papers, 2020 to 2021). "As ERα also has prognostic value in lung cancers, studies have explored LMTK3 as a potential lung cancer biomarker." (PMID 34582708, 2021). "LMTK3 has been identified as a contributor to both the development and progression of lung cancer." (PMID 34582708, 2021).
schizophrenia (3 papers, 2020 to 2024). A major psychotic disorder characterized by abnormalities in the perception or expression of reality. "In this follow-up work, further behavioural experiments of the LMTK3−/− mice were carried out and it was suggested that the knockout mice exhibited behavioural characteristics associated with schizophrenia and bipolar disorder." (PMID 34582708, 2021). "According to that report, LMTK3 KO mice exhibit memory and cognitive dysfunction and are proposed as a mouse model of schizophrenia and bipolar disorders." (PMID 32963255, 2020). "Therefore, this evidence suggests that the LMTK3−/− mice could be exhibiting a behavioural pattern consistent with overlapping bipolar and schizophrenia-like behaviour." (PMID 34582708, 2021).
colorectal cancer (2 papers, 2020). A primary or metastatic malignant neoplasm that affects the colon or rectum. "We evaluated the association between single nucleotide polymorphisms (SNPs) of AKT1 and LMTK3 and the risk of colorectal cancer in a case-control study in Moroccan population." (PMID 33247671, 2020). "The analysis of single nucleotide polymorphisms of AKT1 and LMTK3 could lead to more complete and accurate risk estimates for colorectal cancer." (PMID 33247671, 2020). "However, no variant genotypes of other SNPs (AKT1 (rs1130214, rs3730358, rs1000559097, rs2494737), and LMTK3 (rs8108419, rs9989661)) were associated with a risk of colorectal cancer." (PMID 33247671, 2020).
gastrointestinal stromal tumor (2 papers, 2020 to 2021). "The role of LMTK3 has been widely investigated in gastrointestinal stromal tumours (GISTs)." (PMID 34582708, 2021).
prostate carcinoma (2 papers, 2021 to 2024). A carcinoma that arises from epithelial cells of the prostate gland. "By contrast to the many oncogenic roles of LMTK3, an unexpected function has been described in prostate cancer." (PMID 34582708, 2021). "Overexpression of LMTK3 in prostate cancer cells has been shown to reduce migration and invasion and induce apoptosis in prostate cancer cell lines." (PMID 34582708, 2021). "Additionally, when injected into nude mice, LMTK3-overexpressing prostate cancer cells formed smaller tumours than wild-type cells." (PMID 34582708, 2021).
acute myeloid leukaemia (1 paper, 2021). "A previous tyrosine kinome siRNA study in acute myeloid leukaemia (AML) did not identify LMTK3 as a target, highlighting the heterogeneity of cancers and the importance of identifying relevant populations for specific therapies." (PMID 34582708, 2021).
Anxiety (1 paper, 2023). Intense feelings of nervousness, tension, or panic often arise in response to interpersonal stresses. "LMTK3 was reported to cause behavioral abnormalities such as locomotor hyperactivity and reduced anxiety in mice knock-out models." (PMID 37491581, 2023).
autistic spectrum disorders (1 paper, 2024). "Furthermore, exome sequencing identified a de novo, potentially gene disrupting, LMTK3 mutation in patients suffering in autistic spectrum disorders." (PMID 39520508, 2024).
cognitive decline (1 paper, 2021). "A DMR annotated to LMTK3 was associated with the rate of cognitive decline as measured by the slope of CDR-SB in patients with MCI, and hypomethylation was associated with faster rate of cognitive decline." (PMID 34654479, 2021).
Colon Cancer (1 paper, 2020). "In contrast, they presented an association of LMTK3 rs9989661 in women with Colon Cancer." (PMID 33247671, 2020).
depression (1 paper, 2024). "By contrast, the upregulation of DDC, FGFR2, KIBRA, and MED22, and the downregulation of FSTL1, GRIK4, and LMTK3 in the RagA transgenic mice were negatively correlated with depression." (PMID 39373701, 2024). "Of thirteen depression‐associated DRPs, seven proteins including DDC, FGFR2, KIBRA, MED22, OLIG1, RAI1, SLIT2 were upregulated, whereas six proteins including COX3, CRHBP, CSMD1, FSTL1, GRIK4, and LMTK3 were downregulated." (PMID 39373701, 2024).
Down syndrome (1 paper, 2021). "Probes annotated to LMTK3 have been reported to be differentially methylated in the cortex in patients with Down syndrome and in both the dorsal motor nucleus of the vagus and the substantia nigra in patients with Parkinson disease." (PMID 34654479, 2021).
endometrioid adenocarcinoma (1 paper, 2021). An adenocarcinoma characterized by the presence of malignant glandular epithelial cells resembling endometrial cells. "In short, knockdown of LMTK3 inhibiting cell growth and ERα expression in a well-differentiated ERα-positive endometrioid adenocarcinoma Ishikawa cell line has been first identified." (PMID 34745935, 2021). "We investigated the cytoplastic and nuclear expression levels of LMTK3 between endometrioid adenocarcinoma tissues and adjacent endometrial tissues by immunohistochemistry." (PMID 34745935, 2021). "Inhibitors of LMTK3 may be a possible future treatment for ERα and LMTK3 highly expressed endometrioid adenocarcinoma following appropriate studies." (PMID 34745935, 2021). "However, whether knockdown of LMTK3 inhibits cell growth and ERα expression in the endometrioid adenocarcinoma cell line Ishikawa with a high expression of ERα is still not known." (PMID 34745935, 2021).
non-small cell lung carcinoma (1 paper, 2021). A group of at least three distinct histological types of lung cancer, including non-small cell squamous cell carcinoma, adenocarcinoma, and large cell carcinoma. "Higher levels of serum LMTK3 were found in non-small-cell lung cancer (NSCLC) patients, compared to healthy individuals and those with benign lung lesions." (PMID 34582708, 2021).
ovarian tumors (1 paper, 2026). "LMTK3 protein expression was assessed by immunohistochemistry on tissue microarrays comprising benign, borderline, and malignant ovarian tumors (n = 532)." (PMID 42058596, 2026).
thyroid cancer (1 paper, 2021). "In addition, tissue samples had a higher abundance of LMTK3 mRNA and protein in malignant thyroid tumours compared to benign lesions." (PMID 34582708, 2021). "This study suggests that LMTK3 may play an important role in promoting invasion and cell survival in thyroid cancer." (PMID 34582708, 2021). "ERα is overexpressed in thyroid cancers and oestrogen antagonists have been proposed as a treatment; therefore, LMTK3, as a modulator of ERα, may represent a useful target in thyroid carcinomas." (PMID 34582708, 2021).
cancer (19 papers, 2018 to 2026). A tumor composed of atypical neoplastic, often pleomorphic cells that invade other tissues. "LMTK3 expression levels were implicated in cancer cell invasion, endocrine resistance, poor prognosis, and overall tumor progression in different types of malignancies, and its high expression has been observed in TNBC." (PMID 36672350, 2023). "LMTK3 has been implicated in a broad range of cancers, both as a key component of a variety of oncogenic pathways and as a useful predictive and prognostic biomarker." (PMID 34582708, 2021). "The analysis of single nucleotide polymorphisms (SNPs) of AKT1, an isoform of AKT, and LMTK3 is only a beginning of the molecular pathogenesis understanding and the revelation of mechanisms leading to susceptibility to cancer." (PMID 33247671, 2020). "Lemur tyrosine kinase 3 (LMTK3) has been implicated in cancer prognosis and progression." (PMID 42058596, 2026). "Therefore, the low levels of LMTK3 found in PCa tissue may be associated with a decreased apoptotic rate of cancer cells." (PMID 34064250, 2021). "We have used in silico drug design strategies to discover new inhibitors against the LMTK3 target to stop the mechanistic behavior in the cancer pathway." (PMID 38638686, 2024). "An abundance of LMTK3 in human cancer was related to disease-free survival and suggested a good response to endocrine treatment." (PMID 38638686, 2024). "Despite the increasingly established role of LMTK3 in several cancer types and its central role in a number of well-described signaling pathways, currently there are no drugs in clinical trials targeting this oncogenic kinase." (PMID 36614307, 2023). "Here, we report the inhibitory properties of another compound (C36) against LMTK3, further supporting the rationale that the development and optimization of LMTK3 inhibitors can have prospective value to cancer patients." (PMID 36614307, 2023). "Our result showed that several immune escape related signals on the cancer cell surface are significantly up‐regulated, including PD‐L1, LMTK3 and LAG3." (PMID 36058633, 2023). "Recently, we reported the first tool compound (C28) against LMTK3 that displays anticancer activity in a variety of cancer cell lines and in vivo BC mouse models." (PMID 36614307, 2023). "Here, we report a new tool compound, namely C36, which exhibits anticancer activity against a variety of cancer cell lines that is at least partly mediated by LMTK3." (PMID 36614307, 2023). "Overall, the substantial volume of functional and mechanistic pre-clinical data presented by these studies, along with the newly solved structure of LMTK3, will aid in optimizing LMTK3 inhibitors with prospective value to cancer patients." (PMID 34582708, 2021). "The physiological functions of LMTK3 are poorly characterized as most reports focus on LMTK3 aberrancies in different cancers and the predictive and prognostic relevance of LMTK3." (PMID 34582708, 2021). "Inhibition of LMTK3 decreased the proliferation of different human cancer cell lines, with a concurrent increase in apoptosis in breast cancer cell lines." (PMID 34064250, 2021). "Although the knowledge of its physiological function is largely limited to receptor trafficking in neurons, there is mounting evidence that LMTK3 promotes oncogenesis in a wide variety of cancers." (PMID 34582708, 2021). "This compound slowed cancer growth in xenograft models, demonstrating the therapeutic potential of pharmacological LMTK3 inhibition." (PMID 34582708, 2021). "Although several groups have examined the physiological role of LMTK3, the majority of studies are principally focused on cancer, while a large percentage of this work is related to clinical studies." (PMID 34582708, 2021). "Instead, overexpression of LMTK3 in cancer cell lines decreased cell viability and migratory potential, also inducing apoptosis." (PMID 34064250, 2021).
cancer (continued). "The expression of LMTK3 appeared to be significantly reduced in cancer specimens compared to adjacent normal tissue." (PMID 34064250, 2021). "In bladder cancer cells, LMTK3 overexpression is positively correlated with cancer progression and worse overall survival." (PMID 34582708, 2021). "Emerging evidence showed that LMTK3 played a pivotal role in the tumorigenesis and progression of most cancers." (PMID 32865871, 2020). "Previous research found that LMTK3 is highly expressed in many malignant tumors; its high expression is significantly correlated with the oncogenesis, progression and prognosis of various tumors." (PMID 32865871, 2020). "Eight understudied kinases were found to have hotspot mutations in at least one cancer (CDC42BPA, DYRK1B, DYRK4, LMTK3, MAPK15, NEK7, TSSK1B, and TTBK1), with DYRK4, LMTK3, MAPK15, and NEK7 all having significant hotspot mutations in STAD." (PMID 33205077, 2020). "Lemur tyrosine kinase 3 (LMTK3) is a serine-threonine-tyrosine protein kinase involved in various cancers." (PMID 31178825, 2019). "At mechanistic level, we found that MIR2052HG positively regulated ERα at both mRNA and protein levels via LMTK3 to maintain the cancer cell growth." (PMID 30944027, 2019). "Bearing in mind the increasing interest of 3D cell culture systems in cancer research, we sought to investigate and compare how LMTK3 affects sensitivity to cytotoxic treatment using the 3D models as well as the traditional 2D monolayers." (PMID 29540829, 2018). "Lemur tyrosine kinase-3 (LMTK3; also known as LMR3, TYKLM3, and KIAA 1883) is a predicted dual-specificity protein kinase whose expression levels have been implicated in cancer cell invasion, endocrine resistance, poor prognosis, and overall tumor progression in different types of malignancies." (PMID 38638686, 2024). "Importantly, LMTK3 has been found to be overexpressed in several cancer subtypes, where it contributes to the progression of the disease." (PMID 34582708, 2021). "Here, we review the roles of LMTK3 in health and disease and discuss how this research may be used to develop novel therapeutics to advance cancer treatment." (PMID 34582708, 2021). "Importantly, the data collected from these complimentary approaches will help decode the complex signalling pathways surrounding LMTK3, enabling their integration into the wider network of cancer signalling." (PMID 34582708, 2021). "This demonstrates another avenue through which cancer may become resistant to small molecule inhibitors, via changes in LMTK3 signalling." (PMID 34582708, 2021). "Lemur tyrosine kinase 3 (LMTK3) is an oncogenic kinase that is involved in different types of cancer (breast, lung, gastric, colorectal) and biological processes including proliferation, invasion, migration, chromatin remodeling as well as innate and acquired endocrine resistance." (PMID 29540829, 2018). "With the knowledge that LMTK3 is heavily involved in promoting the progression and development of both ER+ and triple-negative breast cancer, further research into candidate substrates will be crucial to develop therapeutics targeting these pathways to improve cancer treatment." (PMID 34582708, 2021). "Other understudied kinases that score favorably in the majority of cancer cohorts include PKMYT1 (Tchem), DCLK3 (Tchem), BRSK1 (Tchem), ADCK5 (Tdark), and LMTK3 (Tbio)." (PMID 33205077, 2020). "They will be more selective with better structuralfeatures and a potent and specific anti-cancer activity enhancedfor AKT1 and LMTK3." (PMID 31223209, 2018). "Thus, we hypothesized that double inhibition of LMTK3 andAKT1 proteins is a combination therapy with antitumor activity.Therefore, these are new therapeutic targets that can stimulatethe development of new cancer treatment strategies." (PMID 31223209, 2018). "During the carcinogenesis of prostate cells, LMTK3 expression is frequently downregulated at both the mRNA and protein level, as opposed to the upregulation seen in many other cancers." (PMID 34582708, 2021).
cancer (continued). "Design studies of the 3D structure and LMTK3 and AKT1 inhibitors may be useful to block the spread of cancer in patients with CRC." (PMID 33247671, 2020).
tumor (14 papers, 2017 to 2026). "The major driver of this was found to be apoptosis-related as BAX (Bcl-2 associated X-protein) and Caspase-3 were upregulated in the LMTK3-overexpressing tumour tissue and BCL2 (B-cell lymphoma 2) was downregulated." (PMID 34582708, 2021). "Finally, LMTK3 overexpression was also associated with increased tumor cell proliferation as assessed by Ki-67 immunohistochemistry analysis." (PMID 29540829, 2018). "LMTK3 was broadly expressed across all tumor types, with predominant nuclear localization in benign and borderline lesions." (PMID 42058596, 2026). "Lemur tail kinase 3 (LMTK3) is a well-established oncogenic kinase; however, its specific role within the tumor angiogenic microenvironment remains undefined." (PMID 41577842, 2026). "Human lemur tyrosine kinase-3 (LMTK3) is a dual-specificity kinase with a well-established oncogenic involvement in several tumor types, indicating its potential as a therapeutic target." (PMID 38638686, 2024). "Recently, the oncogenic role of lemur tyrosine kinase 3 (LMTK3) has been well established in different tumor types, highlighting it as a viable therapeutic target." (PMID 36614307, 2023). "The relevance of this pathway in vivo was demonstrated in a xenograft mouse model where LMTK3 siRNA reduced the growth of tumours in mice initiated by ER+ MCF7 cells." (PMID 34582708, 2021). "In this paper, we used TMAs to identify that the cytoplasmic LMTK3 expression in endometrioid tissues was higher than that in para-tumor endometrial tissues." (PMID 34745935, 2021). "In aggregate, the studies above underline the pressing need for a better understanding of the elaborate mechanisms involving LMTK3 in different tumour types." (PMID 34582708, 2021). "Evaluation of the data at the mRNA and protein levels confirmed that LMTK3 is overexpressed in tumoural tissues and peritumoural regions compared to healthy white matter." (PMID 34582708, 2021). "In this way, LMTK3 acts as a tumour suppressor that regulates cell apoptosis, modulating the level of anti-apoptotic Bcl-2 and decreasing pro-apoptotic Bax and caspase-3." (PMID 34064250, 2021). "In a mouse model we showed that ectopic overexpression of LMTK3 decreases the efficacy of doxorubicin in reducing tumor growth." (PMID 29540829, 2018). "Ki6713, a tumor proliferation marker, correlates with LMTK3 expression." (PMID 38638686, 2024). "Although information regarding the function of LMTK3 in normal physiology is limited, its oncogenic role has been well established so far in various tumor types, including bladder, lung, and colorectal cancer, among others, highlighting it as a potential therapeutic target." (PMID 36614307, 2023). "However, in the presence of doxorubicin, the tumor growth inhibition was reduced in the MCF7/LMTK3 group (P = 0.0022) compared to the MCF7 one (P < 0.0001), data that were in line with our in vitro results above." (PMID 29540829, 2018). "Furthermore, LMTK3 protein levels were found to positively correlate with endocrine resistance where non-responders to aromatase inhibitors (AIs) had a higher abundance of LMTK3 as measured using immunohistochemistry of tumour tissue." (PMID 34582708, 2021). "MAP3K1, PPM1D, LMTK3, and TGFB1 levels were significantly elevated across all tumor subtypes, with the highest concentrations consistently observed in TNBC (e.g., TGFB1: 544.92 ± 29.81 pg/mL; MAP3K1: 15.44 ± 0.56 ng/mL)." (PMID 41465262, 2025). "a transplant tumour model in nude mice, generated with PC3 cells infected with a recombinant lentivirus-LMTK3 construct." (PMID 34064250, 2021). "In addition, doxorubicin treatment significantly inhibited tumor growth in both the MCF7 and the MCF7/LMTK3 xenograft mice." (PMID 29540829, 2018).
tumor (continued). "Although the hit was not validated, it may suggest that LMTK3 plays a tumour suppressor role in the early development of NSCLC before taking on an oncogenic role in more advanced disease." (PMID 34582708, 2021). "Phosphorylation of RCP at Ser435 by Lemur tyrosine kinase-3 (LMTK3) and of EphA2 at Ser897 by Akt are both necessary to promote Rab14-dependent (and Rab11-independent) trafficking of EphA2 which generates cell:cell repulsion events that drive tumour cells apart." (PMID 28294115, 2017).
LMTK3 also shares sentences with these, for which no sentence is quoted: triple-negative breast carcinoma (3 papers); adenocarcinoma (1); bipolar disorder (1); glioma (1); leukaemia (1); liver disease (1); melanoma (1); Parkinson disease (1).